OR13H1 (olfactory receptor family 13 subfamily H member 1)
Description:
Odorant receptor.
Synonyms: ORX1
Tractability: Antibody: UniProt places it where antibodies can reach, with medium confidence; UniProt predicts a signal peptide or a membrane-spanning region; its Gene Ontology location is reachable by antibodies, with medium confidence.
Gene: Protein-coding gene on chromosome X (131,544,074 to 131,545,000, forward strand). Ensembl gene ENSG00000171054.
Subcellular location: Cell membrane
Pathways (Reactome):
Sensory Perception: Expression and translocation of olfactory receptors
Gene Ontology:
Molecular function: olfactory receptor activity; G protein-coupled receptor activity
Biological process: detection of chemical stimulus involved in sensory perception of smell; G protein-coupled receptor signaling pathway
Cellular component: plasma membrane; membrane
Homologues: Orthologues: chimpanzee OR13H1 (98% identical), rabbit OR13H1 (83% identical), pig OR13H1 (81% identical), tropical clawed frog or5ar28b (46% identical), mouse Or13ae2 (45% identical). Paralogues in human: OR13C4 (46% identical), OR13C9 (46% identical), OR2D2 (46% identical), OR2D3 (46% identical), OR2K2 (46% identical), OR2S2 (46% identical), OR13C2 (46% identical), OR13C3 (45% identical), OR13D1 (45% identical), OR2F1 (45% identical), OR2F2 (45% identical), OR13C8 (45% identical), and 80 more.
Diseases named in the same sentence as OR13H1 in open-access papers:
OR13H1 is named in the same sentence as 2 diseases in open-access papers, as found by Europe PMC text mining. Sharing a sentence is not in itself a finding about the gene and the disease.
OR13H1 shares sentences with these, for which no sentence is quoted: infection (3 papers); breast carcinoma (1).